PCSK9 (proprotein convertase subtilisin/kexin type 9)
Diseases named in the same sentence as PCSK9 in open-access papers (continued):
Sharing a sentence is not in itself a finding about the gene and the disease.
atherosclerosis (continued). "Moving beyond atherosclerosis, PCSK9's implications in abdominal aortic aneurysm (AAA) and coronary artery disease (CAD) bring to light its viability as a therapeutic target in addressing inflammatory processes and cardiovascular risks associated with these conditions." (PMID 40354375, 2025). "PCSK9 inhibitors effectiveness in reducing PWV confirmed the obtained data which also suggest the possible role of PCSK9 as a promising biomarker of CV risk and as a predictor of atherosclerosis independently of menopause and lipid profile." (PMID 40144869, 2025). "Consistently, another study reported a significant reduction in Th17 cells in mice lacking PCSK9, and the results indicated that PCSK9 was associated with T cell programming contributing to the development of atherosclerosis." (PMID 41368357, 2025). "Collectively, these findings suggested that PCSK9 exerted immunomodulatory properties in atherosclerotic plaques and human blood through distinct molecular mechanisms, providing an immunological role for atherosclerosis attenuation beyond LDL-lowering." (PMID 41368357, 2025). "Inhibition of PCSK9 with monoclonal antibodies (mAbs) has become a cornerstone of lipid-lowering therapy in recent decades and has received particular attention in preventing and managing atherosclerosis and later cardiovascular disease." (PMID 41346351, 2025). "In addition to lipid metabolism, PCSK9 has been shown to contribute to atherosclerosis through various mechanisms, such as monocyte infiltration into plaques, macrophage-driven inflammation, and accumulation of oxidized LDL." (PMID 41247317, 2025). "One such strategy involves coupling the catalytic domain of PCSK9 with self-assembling ferritin nanoparticles, which induces an immune response and the production of antibodies against PCSK9, leading to a reduction in lipids and the inhibition of atherosclerosis in various mouse models." (PMID 40722790, 2025). "Furthermore, PCSK9 has been found to directly influence the development of atherosclerosis by affecting the apoptosis of ECs." (PMID 40354375, 2025). "Atherosclerosis and aortic stenosis almost always coexist in clinical practice; therefore, the three groups of drugs- statins, inhibitors of the renin-angiotensin axis, and PCSK9 inhibitors–deserve their place and indication in patients with aortic stenosis." (PMID 40870420, 2025). "Additionally, studies have shown that the concentration of PCSK9 in plasma is elevated in atherosclerotic plaques, further highlighting its prospective function in the progression of atherosclerosis." (PMID 40354375, 2025). "Future research should investigate PCSK9 protein levels in both chronic and acute disease states, exploring their relationship with relevant signaling pathways and their influence on the frequency and severity of heart attacks and atherosclerosis." (PMID 40357205, 2025). "PCSK9 plays a key role in the pathogenesis of LDL receptor-mediated atherosclerosis." (PMID 41247317, 2025). "Consequently, PCSK9‐i synergistically ameliorate lipid profiles, promote plaque stabilization, and retard atherosclerosis progression through both lipid‐dependent and lipid‐independent mechanisms." (PMID 41190281, 2025). "Similarly, in cardiovascular diseases, targeting PCSK9 lowers cholesterol levels, while NLRP3 knockout reduces myocardial inflammation, improving atherosclerosis and decreasing cardiovascular event risk." (PMID 40255230, 2025). "Therefore, PCSK9 has become a key target for the management of hyperlipidemia and atherosclerosis intervention." (PMID 41516253, 2025). "Clarifying these mechanisms could lead to novel therapeutic strategies that integrate PCSK9 inhibitors with lysosome-targeting therapies to optimize the treatment of atherosclerosis, metabolic disorders, and inflammatory CVDs." (PMID 40426881, 2025). "Similarly, 10 μg/kg semaglutide treatment for 18 weeks reduced aortic plaque burden in mice with atherosclerosis induced by Pcsk9 overexpression." (PMID 41178710, 2025).
atherosclerosis (continued). "Furthermore, PCSK9's involvement in atherosclerosis extends beyond LDL cholesterol regulation, impacting vascular inflammation and apoptosis of endothelial cells." (PMID 40354375, 2025). "A PCSK9 inhibitor was found to mitigate atherosclerosis by modulating the small nucleolar RNA host gene 16 (SNHG16)/enhancer of zeste homolog 2 (EZH2)/TNF receptor-associated factor 5 (TRAF5) axis, thereby restraining the migration, proliferation and formation of foam cells by VSMCs." (PMID 40354375, 2025). "Recent studies have clarified the role of Proprotein Convertase Subtilisin/Kexin type 9 (PCSK9) in lipid metabolism, demonstrating its impact on low-density lipoprotein (LDL) levels, which are a key factor in the development of atherosclerosis and associated cardiovascular events." (PMID 40362167, 2025). "The SNP effect on atherosclerosis was blocked by in vivo liver knockdown of Pcsk9 and Bhlhe40." (PMID 40591411, 2025). "For instance, increased PCSK9 gene expression promotes the generation of LDL, while elevated APOC3 gene expression inhibits TG metabolism, both abnormal expressions predispose individuals to atherosclerosis, a significant contributor to myocardial infarction." (PMID 39960900, 2025). "This suggests a potential role for PCSK9 beyond cholesterol elevation in atherosclerosis." (PMID 39445733, 2025). "PCSK9 is conventionally recognized for its role in lipid metabolism and atherosclerosis; however, emerging evidence suggests that it also plays a pivotal role in the processes underlying vascular cell senescence, inflammation, and calcification, which are integral to vascular aging." (PMID 40354375, 2025). "PCSK9 exacerbates atherosclerosis in LDL receptor knockout mice." (PMID 38555386, 2024). "The bibliometric landscape and global research trends related to PCSK9 inhibitors might be helpful in understanding atherosclerosis, as evidenced by publications in the Web of Science Core Collection (WOSCC) database between 2008 and 2022." (PMID 39247108, 2024). "In the blood, PCSK9 inhibitors could have both favorable and unfavorable effects on atherosclerosis, and it is difficult to gain insight into the overall change, mainly because reducing plasma LDL‐C is a highly successful strategy." (PMID 39479289, 2024). "In contrast, PCSK9-induced atherosclerosis was significantly prevented in heterozygous Cap1 knockout mice, suggesting that CAP1 may be a viable target for controlling atherosclerosis." (PMID 38555386, 2024). "TLR4, LOX-1, and PCSK9 have distinctive roles in atherosclerosis development." (PMID 38445291, 2024). "Consequently, lowering plasma levels of low-density lipoprotein cholesterol (LDL-C), which is still the foundation in atherosclerosis treatment, by the inhibition of PCSK9 activity presents a promising therapeutic target." (PMID 39247108, 2024). "Proconvertase subtilisin-kexin 9 (PCSK9) is involved in the atherosclerosis process." (PMID 38532033, 2024). "In such therapy, the kinetics of the reduction of LDL andMDA-modified LDL levels virtually coincide attesting to the predominantutilization of oxidatively modified LDLs, indicating why the use of PCSK9 inpharmacotherapy of atherosclerosis seems to be so promising." (PMID 39228481, 2024). "It is worth mentioning that the vaccine against atherosclerosis may be directed not only against PCSK9." (PMID 38165521, 2024).
atherosclerosis (continued). "In addition, quercetin protects against atherosclerosis via regulation of PCSK9 as well as LXRα and ABCA1." (PMID 37997262, 2024). "Studies evaluating preclinical models show that PCSK9-inhibitor treatment leads to the regression of inflammation and early atherosclerosis biomarkers, mostly via interfering with the nf-κB factor and eNOS pathways, as well as monocyte adhesion to endothelial cells." (PMID 39274253, 2024). "PCSK9 is an outstanding example of a breakthrough in medical science, with advancements in understanding its biological function driving substantial progress in atherosclerosis treatment." (PMID 39770423, 2024). "PCSK9 protein has been reported to participate in cholesterol metabolism and can regulate the progression of many diseases, including atherosclerosis and several tumor types, such as gastric cancer, liver cancer, small bowel cancer, lung cancer, breast cancer, etc.." (PMID 38600469, 2024). "The overexpression of PCSK9 was used to induce atherosclerosis." (PMID 38518516, 2024). "A strong correlation between plasma total cholesterol levels and atherosclerotic lesion area in the aortic root was observed, suggesting cholesterol lowering with a PCSK9 inhibitor itself leads to inhibition of atherosclerosis development and improves plaque morphology." (PMID 39149582, 2024). "In this study, our aim was to ascertain whether PCSK9 possesses the capacity to induce inflammation directly, exacerbating atherosclerosis, independently of alterations in lipid profiles." (PMID 38555386, 2024). "Consequently, the effect of alternative lipid-lowering agents, such as proprotein convertase substilisin/kexin type 9 (PCSK9) inhibitors, on atherosclerosis and atherosclerotic events has been investigated." (PMID 38473748, 2024). "A single injection of an adeno-associated virus vector (AAV) encoding a gain-of-function mutant form of PCSK9, along with an atherogenic diet, induces atherosclerosis in mice and hamsters without genetic modification." (PMID 39149582, 2024). "However, in addition to its role in lipid metabolism, PCSK9 is involved in various processes related to atherosclerosis, affecting both endothelial cell and cardiomyocyte function and proinflammatory pathways." (PMID 38532033, 2024). "Using heterozygous Cap1 knockout mice, we showed that CAP1 could be a therapeutic target that can prevent PCSK9-induced vascular inflammation and atherosclerosis." (PMID 38555386, 2024). "Proprotein convertase subtilisin kexin 9 (PCSK9) that regulates the levels of the LDL receptor has attracted the interest in research in the field of lipidology not only as target for treatment (PCSK9 inhibitors) but also as a marker for atherosclerosis." (PMID 38977131, 2024). "In contrast, those individuals carrying PCSK9 loss‐of‐function variants had increased numbers of their LDL receptors recirculated back to the cell surface, promoting the clearance of LDL‐C from circulation and potentially protecting against atherosclerosis." (PMID 39479289, 2024). "In HCs, PCSK9 significantly correlated with lipid levels and atherosclerosis." (PMID 37759784, 2023). "Previous studies have explored whether serum PCSK9 levels may be a new regulatory biomarker for the early diagnosis of atherosclerosis in T2DM." (PMID 38115042, 2023).
atherosclerosis (continued). "As the SIRT1 small molecule activator with oral activity, SRT3025 increases the expression of hepatic LDL receptors and accumulation of proprotein convertase subtilisin/kexin type 9 (Pcsk9), reduces plasma cholesterol level, inhibits inflammatory response and atherosclerosis." (PMID 36632457, 2023). "Nonetheless, our findings may pave the way for further research aimed at elucidating the correlation between nutrition intake, dyslipidemia, PCSK9, and platelet activation in the pathophysiology of atherosclerosis leading to myocardial infarction." (PMID 37892538, 2023). "Atherosclerosis was induced via AAV8-mediated Pcsk9 overexpression and a high-fat diet." (PMID 37965327, 2023). "Here, we used the following keywords to filter corresponding papers in PubMed: “PCSK9 and atherosclerosis”, “PCSK9 and myocardial infarction”, “PCSK9 and inflammation”, “PCSK9 and platelets”, “PCSK9 and autophagy”, “PCSK9 and apoptosis”, as well as “PCSK9 and pyroptosis”." (PMID 36970356, 2023). "PCSK9 is expressed by various cell types that are naturally involved in inflammation, atherosclerosis, thrombosis, and oncogenesis; thus, the inhibition of this protease may have different pleiotropic effects." (PMID 37109259, 2023). "Thus, it would facilitate the exploration of the crosstalk between PCSK9, autoimmunity and accelerated atherosclerosis." (PMID 37759784, 2023). "Apart from lifestyle interventions (such as smoking cessation, physical activity, and diet), the current cornerstone in atherosclerosis prevention is treating the dyslipidemia with statins and, to a lesser extent, with ezetimibe and proprotein convertase subtilisin/kexin type 9 (PCSK9) inhibitors." (PMID 37175766, 2023). "A close correlation between atherosclerosis and PCSK9 has also been observed." (PMID 36900189, 2023). "Therefore, PCSK9 promotes the development of atherosclerosis dependent on inflammatory regulation in part." (PMID 36970356, 2023). "In line with this evidence, ATHEROREMO-IVUS (The European Collaborative Project on Inflammation and Vascular Wall Remodeling in Atherosclerosis—Intravascular Ultrasound) study showed that the higher the levels of PCSK9, the higher the necrotic core fraction in coronary atherosclerosis." (PMID 37620933, 2023). "In addition, the development of PCSK9 inhibitors has become an important means to treat hyperlipidemia and atherosclerosis." (PMID 38273837, 2023). "This review assesses the current knowledge about how PCSK9 interacts with the immune environment in cancer tissue and how PCSK9 inhibitors could be beneficial in patients treated with ICIs in primary prevention of atherosclerosis." (PMID 36900189, 2023). "Accordingly, a pathogenic loop between PCSK9 and inflammation (i.e., systemic inflammation induces PCSK9, which in turn promotes vascular inflammation) may be speculated, which may contribute to accelerated atherosclerosis in patients with rheumatic diseases." (PMID 37759784, 2023). "Furthermore, PCSK9 siRNA induces inhibition of PCSK9, and inflammatory mediators involved in the pathogenesis of atherosclerosis IL-1α, IL-6, and TNF-α in oxLDL-stimulated THP-1-derived macrophages via suppression of NF-κB nuclear translocation." (PMID 36986246, 2023). "We investigated the impact of PCSK9 activation on inflammation in a TEBV model of atherosclerosis." (PMID 37854060, 2023). "Moreover, Proprotein Convertase Subtilisin/Kexin type 9 (PCSK9) mediated phenotypic transformation, abnormal proliferation, and migration of VSMCs play key roles in accelerating atherosclerosis." (PMID 37208681, 2023). "Atherosclerosis was induced in Nrf2Cdh5tKO and appropriate control mice via adeno-associated viral vector (AAV)-mediated overexpression of murine proprotein convertase subtilisin/kexin type 9 (Pcsk9) in the liver and high-fat diet feeding." (PMID 37965327, 2023).
atherosclerosis (continued). "Studies have proved that hypoxia induces the expression of PCSK9 in cultured cardiomyocytes; on the other hand, PCSK9 induces mitochondrial dysfunction and ROS generation in endothelial cells in the context of atherosclerosis." (PMID 37466835, 2023). "In our study, 50 bioactive compounds docked against the four targets Human Dipeptidyl Peptidase (DPPIV), Sodium-Glucose Cotransporter-2 (SGLT-2) for diabetes, Human Angiotensin-Converting Enzyme (HACE) for hypertension, and Proprotein Convertase Subtilisin Kexin type 9 (PCSK9) for atherosclerosis." (PMID 37823087, 2023). "In addition, the elevated PCSK9 levels were also found to correlate with atherogenic inflammation in SLE, which caused a higher rate of accelerated atherosclerosis—a pathological factor contributing to cardiovascular disease." (PMID 37964871, 2023). "Furthermore, it decreased the expression of NLRP3 inflammasome in macrophages, leading to suppressed macrophage PCSK9 secretion and slower development of atherosclerosis." (PMID 36831039, 2023). "Therefore, PCSK9 was shown to promote ox-LDL-induced atherosclerosis endothelial cell apoptosis via the JNK/p38 MAPK pathway, which in turn reduced the stability of atherosclerotic plaques." (PMID 38273837, 2023). "The increased PCSK9 could accelerate atherosclerosis through activating the TLR4/NF-κB signaling pathway and promoting inflammation." (PMID 36970356, 2023). "Although PCSK9 expression and secretion by ECs may be lower than that by VSMCs, the effects of PCSK9 on EC biology in atherosclerosis cannot be ignored." (PMID 36911736, 2023). "Inhibiting PCSK9 expression or function could impact not only circulating LDL levels but atherosclerosis-promoting inflammation as well." (PMID 37854060, 2023). "Additionally, studies on PCSK9 knockout mice have revealed that removing PCSK9 leads to hypocholesterolemia, reduced atherosclerosis development, and increased sensitivity to statin treatment." (PMID 37860715, 2023). "Studies showed that, through IL-17, PCSK9 could mediate the cross-linking of hyperlipidemia, atherosclerosis, and immune responses." (PMID 35722157, 2022). "Interestingly, emerging data have shown that proprotein convertase subtilisin/kexin type 9 (PCSK9), an key protein of lipid metabolism, is involved in the production of both inflammatory cytokines and atherosclerosis plaque." (PMID 35252378, 2022). "The same established system may be used in future investigations into PCSK9 and platelet activation during atherosclerosis development." (PMID 36005422, 2022). "This inhibition, which was attributed to downregulation of Abca1 gene and ABCA1 protein expression, suggested that PCSK9 can also have extrahepatic effects that may influence relevant steps in the pathogenesis of atherosclerosis." (PMID 36067830, 2022). "Emerging studies have supported the connection between PCSK9, atherosclerosis, and MI." (PMID 35207479, 2022). "Thus, the basis of reduced HbT in PCSK9-ATH mice cannot be attributed to intracranial atherosclerosis." (PMID 35014950, 2022). "In conclusion, we report novel findings of impaired neurovascular function in a novel experimental model of atherosclerosis (PCSK9-ATH) characterised by reduced stimulus-evoked blood volume without any significant alterations to evoked neural activity showing evidence of neurovascular uncoupling." (PMID 35014950, 2022).